KRT8 (keratin 8)
Diseases named in the same sentence as KRT8 in open-access papers (continued):
Sharing a sentence is not in itself a finding about the gene and the disease.
liver cancer (3 papers, 2017 to 2025). An epithelial or non-epithelial malignant neoplasm that arises from the liver. "Further investigations into the mechanism of KRT8 and its potential for intervention in liver cancer are warranted on the basis of similar studies conducted in other cancers." (PMID 39991825, 2025). "We discovered potential drugs for three proteins associated with liver cancer: ASS1 (arginine, aspartic acid, and citrulline), KRT8 (ambroxol, diltiazem, and amikacin), and STOML2 (chortetracycline, chlorzoxazone, and dirithromycin)." (PMID 39991825, 2025). "However, only one study has reported a potential association between the KRT8/KRT18 ratio and liver cancer." (PMID 39991825, 2025). "Therefore, when its expression is altered, KRT8 may facilitate the proliferation of abnormal progenitor cells in the liver, which later transform into liver cancer cells." (PMID 39991825, 2025). "For external validation, we utilized liver cancer GWAS outcome data from a different cohort (ieu-b-4953) to validate the three MR proteins ASS1, KRT8, and STOML2, which presented the highest posterior probability in the colocalization analysis." (PMID 39991825, 2025). "In a single-cell liver cancer dataset, ASS1, KRT8, and STOML2 were expressed mainly in hepatic progenitor cells and malignant cells, with KRT8 predominantly found in hepatic progenitor cells and playing a role in the oncogenesis of malignant liver cells." (PMID 39991825, 2025). "Additionally, feature plots and violin plots were generated for the tier 1 and tier 2 proteins ASS1, KRT8, and STOML2 and the liver cancer marker gene AFP." (PMID 39991825, 2025).
renal carcinoma (3 papers, 2017 to 2023). A carcinoma arising from the epithelium of the renal parenchyma or the renal pelvis. "KRT8 overexpression in renal cancer was associated with cell migration and invasion, and was significantly related to poor survival of patients." (PMID 36999961, 2023). "To identify the genes that are potentially involved in enhancing KRT8 expression in renal cancer cell metastasis, we analyzed the resultant Caki-1-SH cell expression profile using a gene microarray platform." (PMID 29100303, 2017). "IL-11 overexpression attenuated the effects of KRT8 knockdown on renal cancer cell migration and invasion." (PMID 29100303, 2017). "We subsequently found that silencing KRT8 using specific shRNAs decreased renal cancer cell invasion and metastasis abilities, whereas KRT8 overexpression led to significant increases in ccRCC invasion and metastasis ability in vitro." (PMID 29100303, 2017). "To identify the genes potentially involved in enhancing KRT8 expression in renal cancer cell metastasis, we analyzed the resultant Caki-1-SH cell expression profiles using a gene microarray platform and subsequently included differentially expressed genes in functional classification analyses." (PMID 29100303, 2017). "Moreover, KRT8 overexpression in renal cancer cell lines promoted cell migration and invasion." (PMID 29100303, 2017). "To further explore whether KRT8 promotes renal cancer cell migration and invasion through IL-11/STAT3, we overexpressed or knocked down IL-11 to conduct functional studies in renal cancer cells." (PMID 29100303, 2017). "We also demonstrated that KRT8 did not affect renal cancer cell proliferation." (PMID 29100303, 2017).
viral infection (3 papers, 2016 to 2025). "Our in-silico results in asthmatic blood showed that KRT8 mRNA expression was higher in CD8 T lymphocytes in contrast to CD4 T lymphocytes and upregulated significantly in asthmatic who develop cold symptoms due to viral infection." (PMID 34088958, 2021).
acute respiratory distress syndrome (2 papers, 2020 to 2022). Progressive and life-threatening pulmonary distress in the absence of an underlying pulmonary condition, usually following major trauma or surgery. "In sharp contrast, we observed very strong alveolar KRT8 expression in human acute respiratory distress syndrome (ARDS, n = 2) caused by Influenza-A and pneumococcal infection and interstitial lung disease patients with various diagnoses (n = 5)." (PMID 32678092, 2020). "The Krt8+ ADI cells were also found to be persistently present in human fibrotic lungs and appeared in acute respiratory distress syndrome (ARDS) caused by influenza-A and pneumococcal infection as well as interstitial lung disease patients." (PMID 35130980, 2022).
alcoholic liver diseases (2 papers, 2021 to 2025). A disorder caused by damage to the liver parenchyma due to alcohol consumption. "It is noteworthy that one of the keratin genes, KRT8, which was also suggestively associated with decline of memory in females, was found to promote amyloid fibril formation in the liver in alcoholic liver disease." (PMID 40042063, 2025). "Imbalance in KRT8/KRT18 expression occurs in alcoholic liver disease (ALD) and promotes MDB formation." (PMID 34063343, 2021).
atherosclerosis (2 papers, 2013 to 2019). A disease characterized by the build-up of fatty material and calcium deposition in the arterial wall resulting in partial or complete occlusion of the arterial lumen. "This region harbors KRT8 (keratin 8) which may play a role in the endothelial inflammatory disease, as atherosclerosis." (PMID 23675383, 2013).
breast invasive carcinoma (2 papers, 2021). "There were increased autoantibodies in invasive breast cancer to ARPC2 (p < 0.0001 for controls) and KRT8 (p = 0.0004 for controls)." (PMID 33976232, 2021).
carcinosarcoma (2 papers, 2012 to 2017). A malignant tumor composed of a mixture of carcinomatous and sarcomatous elements. "Immunohistochemical analysis showed that KRT8 was expressed in the epithelial component of all five carcinosarcoma MBC cases." (PMID 29137351, 2017). "Among both carcinosarcomas and metaplastic tumors, we observed dual expression of mesenchymal (Vimentin) and epithelial (Keratin-8) markers, which are mutually exclusive lineage markers in the normal gland." (PMID 23173005, 2012).
chondrosarcoma (2 papers, 2022 to 2023). A malignant cartilaginous matrix-producing mesenchymal neoplasm arising from the bone and soft tissue. "Expression of Krt8, Krt18, and Lgals3, which are notochord markers, was observed in cluster 6, suggesting that dysregulated differentiation might also occur in mesenchymal chondrosarcoma, unlike normal chondrocytic differentiation." (PMID 37212282, 2023).
colorectal adenocarcinoma (2 papers, 2017 to 2024). The most common type of colorectal carcinoma. "Moreover, comparing the samples from young and old donors, four DEGs (HOXB5, KRT8, MSX1, NFE2L3) in the samples from old donors were specifically expressed in colorectal adenocarcinoma (4/33, 12%)." (PMID 38520027, 2024).
coronary artery disease (2 papers, 2019 to 2025). "A self-antigen, keratin-8 was found to increase the levels of PD-1 appearance in the human peripheral blood mononuclear cells (PBMCs) as against PBMCs obtained from coronary artery disease patients." (PMID 40255399, 2025).
cryptogenic cirrhosis (2 papers, 2017 to 2025). "KRT8 is associated with diseases such as cryptogenic cirrhosis and familial cirrhosis." (PMID 39991825, 2025).
Fibroadenoma (2 papers, 1996 to 2021). A benign tumor of the breast characterized by the presence of stromal and epithelial elements. "In women with fibroadenoma, an autoantibody response occurred against VPS35 (p = 0.007 compared to control women), SERBP1 (p < 0.0001 compared to control women), KRT8 (p = 0.03 compared to control women), and PDIA6 (p = 0.003 compared to control women)." (PMID 33976232, 2021).
head and neck carcinoma (2 papers, 2017 to 2024). A carcinoma that arises from the head and neck region. "KRT8 was positively expressed in head-and-neck squamous cell carcinomas and metastases, but not in hyperplastic leukoplakia, indicating that KRT8 can be used as an attractive marker molecule for differentiating between diagnoses of leukoplakia and head-and-neck carcinomas." (PMID 29100303, 2017).
Hepatic fibrosis (2 papers, 2021 to 2022). The presence of excessive fibrous connective tissue in the liver. "In the “hepatic fibrosis” pathway, eight fibrogenic genes (Pparg, Krt8, H2-Ab1, H2-Aa, Nqo1, Il33, and Ltb) are upregulated, and one gene (Serpina1c) is downregulated." (PMID 33916843, 2021). "KRT8 expression is high in patients with advanced liver fibrosis." (PMID 36362037, 2022).
interstitial lung disease (2 papers, 2020 to 2024). A diverse group of lung diseases that affect the lung parenchyma. "IL11 is similarly expressed by KRT8+ alveolar epithelial cells lining fibrotic lesions in a mouse model of interstitial lung disease." (PMID 39358385, 2024). "In interstitial lung disease, aberrant KRT8+ basaloid cells impair alveolar repair mechanisms." (PMID 39358385, 2024). "We analyzed single cell RNA sequencing datasets of human interstitial lung disease and found the profibrotic Interleukin-11 (IL11) cytokine to be highly and specifically expressed in aberrant KRT8+ basaloid cells." (PMID 39358385, 2024).
metastatic carcinoma (2 papers, 2021 to 2023). A carcinoma which has spread from the original site of growth to another anatomic site. "Results revealed a higher Mesenchymal markers in primary cancer cells (e.g., NCAM1, LAMB1, SERPINE1, TCF4, VIM, ZEB1, and ZEB2) and a higher Epithelial markers in metastatic cancer cells (e.g., CDH1, CLDN4, ELF3, EPCAM, KRT18, KRT7, and KRT8)." (PMID 37202394, 2023).
neuroblastoma (2 papers, 2016 to 2021). Neuroblastoma (NB) is the most common solid, extracranial childhood tumor. "Keratins are cytoskeleton proteins; however, the cell-surface presence of keratins is found in several cancer cells, including breast (K1), neuroblastoma (K1), and colon (keratin 8) cancer cells, and these proteins are linked to tumor metastases." (PMID 34063098, 2021).
pancreatic disease (2 papers, 2022 to 2024). "Recent studies of pancreatic diseases also focused on the expression of KRT8." (PMID 35958278, 2022).
papillary thyroid cancer (2 papers, 2018 to 2021). "Next, KRT8 protein expression was measured in tumor and non-malignant patient samples (n = 17): eight patients with ATC, five with papillary thyroid cancer (PTC), and four with benign multinodular disease (BND)." (PMID 29443941, 2018).
renal cell carcinoma (2 papers, 2020 to 2022). "In renal cell carcinoma K8 overexpression promoted cell migration and invasion by increasing the expression of IL-11 and triggering the STAT3-signaling pathway, establishing the significance of KRT8-IL-11 axis in metastasis." (PMID 33171868, 2020).
skin cancer (2 papers, 2019 to 2022). "Ectopic KRT8 also results in abnormal epidermal differentiation and a dramatic increase in the malignant progression of the skin tumors." (PMID 31466283, 2019). "For example, previous studies have reported that KRT8, KRT18, and KRT19 are expressed in most cancers, including skin cancer, whereas our analysis revealed that their expression is low in skin cancer samples." (PMID 35267493, 2022).
adrenocortical carcinoma (1 paper, 2018). "Genomic alterations in KRT8 were present in 83 cases, ranging from 0 to 11% (mean 1.9%) of cases by cancer type, with the highest prevalence of KRT8 genomic alterations observed in adrenocortical carcinoma (11.4%), stomach adenocarcinoma (4.9%), and uterine endometrial carcinoma (4.1%)." (PMID 29443941, 2018).
alcoholic cirrhosis (1 paper, 2022). "Given the limited therapeutic options available for the treatment of ASH and alcoholic cirrhosis, targeting KRT8 aggregation could present a new route for drug development, as has been done with other amyloid diseases." (PMID 35637421, 2022). "Given our structural and biochemical findings on KRT8 aggregation, as well as the fact that MDBs are most frequently observed in ASH and alcoholic cirrhosis, we next sought to explore KRT8 aggregation in the context of alcoholic liver disease." (PMID 35637421, 2022).
anaplastic thyroid carcinoma (1 paper, 2022). "Keratins 8 (KRT8) protein was reported to bind to annexin A2, a protein known to mediate apoptosis as well as the redox pathway in anaplastic thyroid carcinoma (ATC)." (PMID 36672532, 2022).
basal cell tumors (1 paper, 2020). "Keratins 8 (KRT8) is a key participation factor of keratinization, which exists abnormal performance in basal cell tumors." (PMID 31794632, 2020).
Chlamydial infections (1 paper, 2016). "Chlamydial infections have been suggested to break down these junctions and disrupt epithelial cell integrity through degradation of nectin-1 and keratin-8 and -18, as well as sequestration of β-catenin and E-cadherin." (PMID 26829550, 2016).
chronic lung disease (1 paper, 2020). According to the definitions of the American and British Thoracic Societies, including pulmonary functional tests, X-rays, and CT scans for items such as fibrosis, bronchiectasis, bullae, emphysema, nodular or lymphomatous abnormalities. "To further validate that KRT8+ alveolar cells can also be observed in human acute lung injury and chronic lung disease associated with alveolar injury, we stained human tissue sections and did not detect any expression of KRT8 in the alveolar space of non-injured control lungs (n = 7)." (PMID 32678092, 2020).
diabetic nephropathy (1 paper, 2025). "CCT3 may be a marker of diabetic nephropathy and KRT8 has been shown to be involved in the regulation of blood glucose." (PMID 40502754, 2025).
glioblastoma (1 paper, 2022). The most malignant astrocytic tumor (WHO grade IV). "Recent studies revealed that the overexpression of KRT8 could be also found in glioblastoma." (PMID 35958278, 2022).
gynecologic cancers (1 paper, 2022). "To directly study the development of these gynecologic cancers from epithelial and mesothelial cells only, we utilized a new Cre-expressing adenovirus under the control of the Krt8 promoter (Ad-K8-Cre)." (PMID 35159108, 2022).
hair disorder (1 paper, 2020). "We used our highest resolution keratin 1B structure as a template for homology-modeling the 1B heterotetramers of keratin 5/14 (associated with blistering skin disorders), keratin 8/18 (associated with liver disease), and keratin 74/28 (associated with hair disorder)." (PMID 32927888, 2020).
heart failure (1 paper, 2019). Inability of the heart to pump blood at an adequate rate to meet tissue metabolic requirements. "Keratin 8 is found in atherosclerotic plaques, neointimal and synthetic smooth muscle cells, and saphenous vein grafts, and its ectopic expression has been linked to heart failure." (PMID 30811493, 2019).
hepatoblastoma (1 paper, 2025). Hepatoblastoma (HB) is a malignant hepatic tumor and is the most common pediatric liver cancer. "We first performed a transcriptomic evaluation of the two well‐recognized hepatoblastoma cell lines, HepG2 and HUH6, using Pearson's analysis with gene signatures in the public GSE168997 dataset to elucidate IGF2′′s role in hepatoblastoma (AFP, DUSP9, GPC3, DLK1, MYC, EPCAM, KRT8, and LIN28B)." (PMID 40271711, 2025).
Hyperglycemia (1 paper, 2018). An increased concentration of glucose in the blood. "If the hepatic levels of NAD+ and of keratin 8 and GKRP deacetylation reflect hepatic Sirt2 activity, it is plausible that a decrease in Sirt2 activity in the obese diabetic livers results in compromised regulation of HGU and glucokinase translocation by postprandial hyperglycemia." (PMID 29296001, 2018).
Hyperkeratosis (1 paper, 2025). Hyperkeratosis is a histopathological term defining a thickened stratum corneum and may be present in many different skin conditions, with many possible overlaps. "Given the hyperkeratosis observed in VDR-KO rats through HE staining, we conducted Western blotting using the antibody against the keratin marker Krt14 and anti-pan-keratin antibody (PCK26), which detects rat keratin 1 (66 kDa), keratin 5 (58 kDa), and keratin 8 (52 kDa)." (PMID 39796272, 2025).
invasive ductal carcinoma (1 paper, 2013). "KRT8 is one of the major intermediate filament proteins expressed in single-layered epithelia of the gastrointestinal tract, and KRT8/18 expression differentiates distinct subtypes of grade 3 invasive ductal carcinoma of the breast." (PMID 24099319, 2013).
Meesmann corneal dystrophy (1 paper, 2021). Meesmann corneal dystrophy (MECD) is a rare form of superficial corneal dystrophy characterized by distinct tiny bubble-like, round-to-oval punctate bilateral opacities in the central corneal epithelium, and to a lesser extent in the peripheral cornea, with little impact on vision. "Krt8/keratin 8 was shown to protect against degeneration of retinal pigment epithelium under oxidative stress, and KRT3 and KRT12 gene mutations associated with Meesmann corneal dystrophy." (PMID 35118070, 2021).
meningioma (1 paper, 2023). A generally slow growing tumor attached to the dura mater. "Keratin filaments and desmosomes have also been described in “arachnoidal sheaths” of some higher vertebrates, and keratin 8 immunoreactivity detected in cells of normal human spinal leptomeninx and various meningiomas." (PMID 37858244, 2023).
nonalcoholic steatohepatitis (1 paper, 2022). "KRT8/KRT18 variations listed in the ClinVar database may be involved in nonalcoholic steatohepatitis (NASH), in oxidative stress to the liver, indirectly leading to cirrhosis, and in increased formation of fibrosis during chronic hepatitis C infection." (PMID 34991727, 2022).
progeria (1 paper, 2022). "Some genes that are downregulated during aging are upregulated in progeria patients (KRT8, KRT18, UCP2, ADAMTS15, ACTN4P1) while others (ACKR4) are upregulated in nonagenarians but downregulated in children suffering from HGPS." (PMID 36289702, 2022).
psoriasis (1 paper, 2025). An autoimmune condition characterized by red, well-delineated plaques with silvery scales that are usually on the extensor surfaces and scalp. "Among the top 10 downregulated and top 10 upregulated DEG, we identified several key genes related to psoriasis, including Krt25, Krt8, Muc16, Slc5a7, Reg3b." (PMID 39665264, 2025).
rheumatoid arthritis (1 paper, 2019). A chronic, systemic autoimmune disorder characterized by inflammation in the synovial membranes and articular surfaces. "Keratin 8 was reported as an autoantigen in uveitis and in rheumatoid arthritis and may be involved in immune escape mechanisms by cancer cells." (PMID 30811493, 2019).
Ta (1 paper, 2005). "Consistent with the literature, we found members of the cytokeration family, especially KRT7, but also KRT8 highly expressed in Ta tumours." (PMID 16265353, 2005).